ENSG00000212415
Synonyms: LOC124900367
Gene: Small nucleolar RNA gene on chromosome 15 (32,970,727 to 32,970,791, forward strand). Ensembl gene ENSG00000212415.
Gene Ontology:
Biological process: RNA processing
Cellular component: nucleolus
Homologues: Orthologues: zebrafish snord80.1 (58% identical), zebrafish snord80.2 (58% identical). Paralogues in human: SNORD77B (88% identical).